FGF23 (fibroblast growth factor 23)
Diseases named in the same sentence as FGF23 in open-access papers (continued):
Sharing a sentence is not in itself a finding about the gene and the disease.
chronic kidney disease (continued). "In chronic kidney disease (CKD), the hyperphosphaturic osteocyte-derived hormone FGF-23 increases to compensate for phosphate retention and further inhibits renal 1α-hydroxylase expression, and induces the expression of 24-hydroxylase responsible for the degradation of 1,25-(OH2)D." (PMID 28346348, 2017). "Therefore, FGF23 is not only a phosphaturic but also acalcium- and sodium-conserving hormone, a finding that may have important implications forthe pathophysiology of chronic kidney disease." (PMID 29096595, 2017). "Indeed, FGF23 signaling promotes proliferation in myeloma cells, while increase of FGF23 levels in serum were observed in cancer patients, and were also elevated in patients with non-cancerous diseases, such as hypophosphatemic rickets and chronic kidney diseases." (PMID 29108258, 2017). "Serum FGF23 levels are elevated in patients with chronic kidney disease (CKD)." (PMID 27504998, 2016). "Fibroblast growth factor 23 (FGF23), elevated in chronic renal failure, increases atrial arrhythmogenesis and dysregulates calcium homeostasis." (PMID 27713141, 2016). "In the Chronic Renal Insufficiency Cohort (CRIC) study, the median C-terminal FGF23 was 145 RU/mL (IQR 96–239) in patients with a mean eGFR of 42.8 ± 13.5 ml/min/1.73 m2." (PMID 27495287, 2016). "Circulating FGF-23 concentrations rise substantially with chronic kidney disease (CKD)." (PMID 25647414, 2015). "Decreased TM-Klotho, described in experimental chronic kidney disease (CKD), prevents actions of FGF23 and lessens circulating s-Klotho." (PMID 25873958, 2015). "FGF-23 is increased in patients with chronic kidney disease (CKD)." (PMID 26462160, 2015). "In chronic kidney disease (CKD), FGF-23 increases early in the course of the deterioration of kidney function, and has been proposed to be a physiological response that protects the organism from the adverse effects of phosphate retention by facilitating phosphate excretion." (PMID 26024521, 2015). "Chronic kidney disease (CKD) may lead to reduced 1.25-dihydroxyvitamin D3 levels by limiting the amount of 1α hydroxylase or suppressing its action through increased fibroblast growth factor-23." (PMID 25229495, 2014). "In addition to predicting the prognosis in chronic kidney disease, determination of the correlation between decreased glomerular filtration rate and increased levels of FGF-23 may be an important target, especially in treatment of secondary hyperparathyroidism." (PMID 25295189, 2014). "Notably, recent studies have shown that serum FGF23 levels gradually increase during the progression of chronic kidney disease (CKD), whereas renal α-KL expression declines." (PMID 24466013, 2014). "We provide novel data that demonstrate that FGF-23 levels are elevated in acute kidney injury, suggesting that FGF-23 dysregulation occurs in acute kidney injury as well as chronic kidney disease." (PMID 21906363, 2011). "In patients with end-stage renal disease (ESRD), FGF-23 levels can be extremely high and were shown to be predictors of bone mineralization, left ventricular hypertrophy, vascular calcification, and mortality." (PMID 20593414, 2010). "In chronic kidney disease (CKD), FGF-23 levels rise in parallel with the decline in renal function long before a significant increase in serum phosphate concentration occurs." (PMID 21234310, 2010). "Background/Objectives: Chronic kidney disease-mineral and bone disorder (CKD-MBD) is characterized by complex interactions between parathyroid hormone (PTH), fibroblast growth factor 23 (FGF23), phosphate, calcium, and vitamin D, yet clinical decisions are often based on static individual values." (PMID 42194651, 2026). "Several diseases have been described that present with elevated levels of FGF23, such as X-linked hypophosphatemia (XLH), autosomal dominant and recessive hypophosphatemic rickets, fibrous dysplasia, tumor-induced osteomalacia, and chronic kidney disease (CKD)." (PMID 41426862, 2025).
chronic kidney disease (continued). "Searches were performed in PubMed, Scopus, and Web of Science using combinations of keywords such as “cardiorenal syndrome,” “biomarkers,” “heart failure,” “acute kidney injury,” “chronic kidney disease,” and specific marker names (e.g., NGAL, KIM-1, cystatin C, CA125, bio-ADM, FGF-23, etc.)." (PMID 41157213, 2025). "Burosumab, a monoclonal antibody targeted against FGF-23 and approved for TIO and X-linked hypophosphatemia (XLH), has not been extensively studied in patients with chronic kidney disease (CKD) and elevated FGF-23 levels." (PMID 41583152, 2025). "In chronic kidney disease (CKD), the disturbance of the fibroblast growth factor 23 (FGF23) /1,25-dihydroxyvitamin D [1,25 (OH)2D]/ parathormone (PTH) axis and the irregulation of calcium and phosphate jointly lead to decreased bone mass and increased fragility fractures." (PMID 38730354, 2024). "However, when renal function is compromised, as it is in chronic kidney disease (CKD), phosphate excretion is impaired, leading to persistent hyperphosphatemia and continuous stimulation of FGF23." (PMID 39666728, 2024). "In end-stage renal disease (ESRD), FGF23 levels become exceptionally high." (PMID 38846254, 2024). "A linear relationship had been described between FGF23 and cardiovascular mortality, independent of the chronic kidney disease status in a general adult population." (PMID 38818505, 2024). "In the case of AKI and chronic kidney disease (CKD), IL-6 increases fibroblast growth factor 23 levels, which may contribute to phosphaturia and hypophosphatemia, thus affecting renal function." (PMID 37010812, 2023). "In the early stage of LVH without chronic kidney disease, serum FGF23 levels did not change but cardiac FGF23 expression significantly increased along with LVH progression." (PMID 38174329, 2023). "While the importance of FGF23 is well-known in phosphate-wasting disorders and in chronic kidney disease, data on FGF23 levels and its regulation in PHPT are not concordant before and after successful parathyroidectomy." (PMID 37065752, 2023). "In this study, we investigated the expression of fibroblast growth factor 23 (FGF23) and D-serine in maintenance hemodialysis (MHD) patients with end-stage renal disease (ESRD) complicated with hearing impairment and further investigated the correlation between FGF23/D-serine and hearing impairment." (PMID 36649363, 2023). "Since then, a large number of clinical studies have shown that high plasma concentrations of FGF23 are associated with left ventricular hypertrophy (LVH), heart failure, and mortality in the general population, and especially in patients with chronic kidney disease (CKD)." (PMID 36909314, 2023). "Therefore, the decreased level of iFGF23 in INHD was not related to the difference in active vitamin D. PTH is another potential regulator of FGF23 in chronic renal failure since PTH and FGF23 were both elevated at the same time." (PMID 35801203, 2022). "FGF23 has been proposed as a promising biomarker for the prediction of adverse outcomes, including cardiovascular disease (CVD) and mortality, in patients with chronic renal failure." (PMID 36440231, 2022). "Meanwhile, FGF-23 was also elevated in ULMACD patients with previous chronic renal failure (P = 0.009) compared to those without." (PMID 36132198, 2022). "Moreover, several acute and chronic diseases including chronic kidney disease (CKD) or further cardiovascular disorders are characterized by early rises in the plasma FGF23 level pointing to further mechanisms effective in the regulation of FGF23 under pathophysiological conditions." (PMID 35084563, 2022). "Obviously, this is not valid in the population with chronic renal failure since in these patients FGF23 acts by protecting the body against excessive phosphate load." (PMID 36440231, 2022).
chronic kidney disease (continued). "The measurement of Fibroblast growth factor 23 (FGF23) may be useful in the diagnosis and management of abnormal phosphate metabolism in both patients with preserved renal function or with chronic kidney disease (CKD)." (PMID 36440231, 2022). "FGF-23 level was increased in patients with both previous heart failure (P = 0.046) and chronic renal failure (P = 0.009) compared to those without." (PMID 36132198, 2022). "It was demonstrated that in patients with chronic kidney disease (CKD), FGF-23 levels rise in parallel with declining renal function, even before a significant increase in serum phosphate concentration can be detected and a compensatory decrease in Klotho protein concentration is observed." (PMID 34603200, 2021). "While studies have shown possible FGF-23 effects on CV outcomes in patients with chronic kidney disease, this has not been proven in cases of TIO." (PMID 34268038, 2021). "Likewise, a meta-analysis evaluating the association between FGF23 and cardiovascular outcomes found no significant exposure-response relationship in patients with and without chronic kidney disease (CKD)." (PMID 34778257, 2021). "Interestingly, in patients with chronic renal failure, the VDR genetic profile seems to perturb the FGF23 expression and consequently the physiological action of FGF23 mediated by FGF receptor and co-receptor Klotho." (PMID 32899460, 2020). "Interestingly, the FGF23/FGFR4 axis has been extensively studied in the myocardium, and when challenged by additional chronic kidney disease or high-phosphate diet, Fgfr4−/− mice also demonstrate left ventricular hypertrophy." (PMID 32793609, 2020). "Interestingly, Fibroblast Growth Factor 23 (FGF23) was shown by several studies to be a positive predictor for mortality or cardiovascular complications in heart failure, chronic kidney disease and sepsis." (PMID 32309615, 2019). "During chronic kidney disease (CKD), alterations in bone and mineral metabolism include increased production of the hormone fibroblast growth factor 23 (FGF23) that may contribute to cardiovascular mortality." (PMID 31044094, 2019). "Emerging data from the chronic kidney disease (CKD) field suggest that both iron deficiency and EPO lead to an up-regulated expression and concomitant cleavage of a phosphate-regulating hormone, fibroblast growth factor 23 (FGF23), another risk factor for mortality." (PMID 31170159, 2019). "Furthermore, circulatory FGF23 is high in patients with chronic kidney disease (CKD)." (PMID 29515522, 2018). "Long-term supplementation with modest quantities of EPA-DHA or ALA does not reduce plasma FGF23 levels when added to cardiovascular medication in post-myocardial patients with chronic kidney disease." (PMID 29137111, 2017). "The main finding of this study is that in post-myocardial infarction patients with chronic kidney disease (eGFR < 60 mL/min/1.73 m2), low dose n-3 fatty acid supplementation did not reduce plasma C-terminal FGF23 levels." (PMID 29137111, 2017). "Previous reports have shown that FGF-23 is an early marker of mineral disorder in chronic kidney disease, which has a phosphaturic effect (thus it promotes an increase of uFEP values) in order to avoid the development of hyperphosphatemia, which contributes to the progression of CKD." (PMID 29240673, 2017). "In chronic kidney disease (CKD), FGF23 levels rise as renal function declines." (PMID 28659167, 2017). "Increased concentration of fibroblast growth factor 23 (FGF-23) and decreased levels of soluble Klotho (sKL) are linked to negative clinical outcomes among patients with chronic kidney disease and acute kidney injury." (PMID 28130714, 2017). "On the other hand, few studies have clearly demonstrated the relationship between FGF23 level and left ventricular hypertrophy among subjects without chronic kidney disease (CKD; i.e., CKD stage G1 or G2)." (PMID 27400031, 2016).
chronic kidney disease (continued). "In patients with chronic kidney disease (CKD), FGF23, an endocrine hormone that can regulates phosphorus homeostasis, inhibits the activation and recruitment of neutrophils, and FGF23 neutralization in mouse CKD models restore leukocyte recruitment and host defense." (PMID 27721573, 2016). "Interestingly, a significant relationship between FGF-23 and PTH was previously documented in chronic kidney disease and HF patients." (PMID 26308451, 2015). "The pathophysiological downside of this regulation may occur in diseases such as chronic kidney disease, where PTH and FGF23 are chronically elevated due to decreased renal 1,25(OH)2D production and phosphate retention." (PMID 24434184, 2014). "In chronic kidney disease (CKD), circulating levels of intact FGF-23 are dramatically increased." (PMID 25208316, 2014). "Next, we analyzed the association of age, high blood pressure (systolic blood pressure≥140 mmHg and/or diastolic blood pressure≥90 mmHg), chronic kidney disease (eGFR<60 mL/min.1.73 m2), UA, intact PTH, and FGF23 with LV hypertrophy by multivariate logistic regression analysis." (PMID 24340056, 2013). "Chronic kidney disease (CKD) related mineral bone disorders persist after kidney transplantation, but little is known about the relationship between fibroblast growth factor-23 (FGF-23) and mineral metabolism in prevalent post-transplant patients." (PMID 22811905, 2012). "Intact FGF-23 was measured in order to avoid measurement of fragments that accumulate in end-stage renal disease and do not probably reflect endogenous FGF-23 production." (PMID 20107581, 2009). "Furthermore, clinical data from patients with chronic kidney diseases should be useful in evaluating the interactions among calcitriol, PTH, and FGF23." (PMID 19838340, 2009). "Additionally, high extracellular phosphate levels can disrupt calcium homeostasis through the systemic interactions of hormones such as fibroblast growth factor 23 (FGF23), vitamin D and parathyroid hormone (PTH), especially under pathological conditions such as chronic kidney disease (CKD)." (PMID 42193909, 2026). "The FGF23/Klotho axis has a well-established role in the pathogenesis of chronic kidney disease–mineral and bone disorder (CKD-MBD), with FGF23 levels rising in the early stages of CKD." (PMID 41367909, 2025). "The fibroblast growth factor-23 (FGF-23)–Klotho axis plays a major role in chronic kidney disease-mineral and bone disorder (CKD-MBD) in patients with CKD." (PMID 39839279, 2024). "Intact Fibroblast Growth Factor 23 (i-FGF23), a phosphaturic hormone that contributes to the anemia of inflammation, especially in chronic kidney disease, has not been studied extensively in acute inflammatory diseases in pediatric patients with no comorbidity." (PMID 39336155, 2024). "We found increased levels of IL-6, IL-8, CD40, PDL-1, FGF-23, IL-15-RA, TGF-a, and CCL25 that persist at two months after LTA in IKF patients, consistent with current concepts of inflammation as a crucial pathophysiological mechanism in the development of chronic kidney disease." (PMID 39440014, 2024). "In this study, we investigated the correlation between FGF23/D-serine and hearing impairment in MHD patients with ESRD, which is expected to provide a theoretical basis for the treatment of hearing impairment induced by chronic renal failure and a potential target for drug therapy." (PMID 36649363, 2023). "It is well known that FGF23 circulating levels are upregulated in chronic kidney disease, and we have shown recently that FGF23 per se does not exert a pro-inflammatory effect on the “healthy” bronchial epithelium, whereas the COPD epithelium shows increases in IL-1β when stimulated with FGF23." (PMID 37763754, 2023). "Klotho and fibroblast growth factor 23 (FGF23) are early laboratory parameters of chronic kidney disease (CKD)-mineral bone disorder (MBD), and the Klotho/FGF23 axis plays an important role in this disorder." (PMID 35872753, 2022).
chronic kidney disease (continued). "Moreover, individuals with chronic kidney disease, even in early stages of renal failure, when phosphate and PTH levels were still within the normal ranges, were shown to have increased concentration of FGF23 with a concomitant decrease of serum Klotho." (PMID 34603200, 2021). "However, the Chronic Kidney Disease in Children (CKiD) study enrolled children with mild-to-moderate pre-dialysis CKD, respectively, concluded that a high plasma FGF23 concentration above 170 RU/ml together with estimated GFR ≥ 45 ml/min per 1.73 m2 is associated with a higher prevalence of LVH." (PMID 34422725, 2021). "In patients affected with chronic kidney disease (CKD), serum PTH increases due to a complex pathophysiological mechanism involving phosphorus (P), Fibroblast Growth Factor−23 (FGF-23), vitamin D metabolites and iCa." (PMID 33348538, 2020). "The beneficial effect was evident in both patients with and without chronic kidney disease but did seem to be numerically greater in patients with eGFR < 60 ml/min/1.73 m2, who should also be expected to have the highest levels of circulating FGF-23." (PMID 32998751, 2020). "This event is termed chronic kidney disease-mineral bone disorder (CKD-MDB), which refers to renal dysfunction and altered levels of calcium, phosphate, PTH, 1-25-dihydroxyvitamin D and FGF23." (PMID 31461904, 2019). "In experimental models of chronic renal failure blockade of the renin-angiotensin system (RAS), the endothelin (ET) system, pharmacological and mechanical inhibition of the sympathetic nervous system, and blockade of the FGF23-axis were also shown to be successful." (PMID 30186632, 2018). "Recent evidence has highlighted the central pathophysiological role of chronic kidney disease-mineral and bone disorder (CKD-MBD) with hyperphosphatemia and high fibroblast growth factor 23 (FGF23) levels in these patients." (PMID 30087898, 2018). "Serum FGF23 levels are highly elevated in patients with chronic kidney disease (CKD), and it is likely that FGF23 directly contributes to the high rates of LVH and cardiac death in CKD." (PMID 28512310, 2017). "Increased fibroblast growth factor 23 (FGF23), a bone-derived hormone involved in the regulation of phosphate and vitamin D metabolism, has been related to the development of cardiovascular disease (CVD) in chronic kidney disease patients and in the general population." (PMID 26193703, 2015). "In contrast, a monoclonal FGF23 neutralizing antibody did not protect rats with chronic kidney disease from cardiovascular injury, indicating that FGF23 might not have direct effects on the heart." (PMID 24046748, 2013). "Whether or not the elevated serum FGF-23 concentrations found in chronic renal insufficiency are sufficient to correct the hyperphosphatemia of early and advanced CRF is not completely clear." (PMID 18288501, 2008). "Fifth, the presence of chronic kidney disease (CKD) at baseline may influence the relationship between canagliflozin and levels of FGF-23 and hsCRP; this may be evaluated in SGLT2 inhibitor trials among patients with CKD." (PMID 41151250, 2025). "Obesity may increase FGF23 production in the absence of chronic kidney disease." (PMID 40649786, 2025). "However, its limitations include a lack of characterization of i:cFGF23 in non-healthy individuals, such as those with chronic kidney disease, and the heterogeneous units utilized for C-terminal FGF23, which necessitates a semi-quantitative approach for interpreting the i:cFGF23 ratio." (PMID 41445556, 2025). "As a consequence of this, from the early stages of chronic kidney disease (CKD), parathyroid hormone (PTH) and fibroblast growth factor 23 (FGF-23), two hormones with phosphaturic activity, are over-secreted with the aim to regulate the serum concentration of this ion." (PMID 39407717, 2024).